CAV1 (caveolin 1)
Diseases named in the same sentence as CAV1 in open-access papers (continued):
Sharing a sentence is not in itself a finding about the gene and the disease.
tumor (continued). "Therefore, the enriched Cav-1 in tumor vessels provides an interesting opportunity for Cav-1-targeted therapies." (PMID 28546853, 2017). "Initially, Cav-1 protein has been shown to play a role in tumor suppression." (PMID 28828003, 2017). "The downregulation of Cav-1 is a major characteristic of CAFs, and existing studies have indicated that CAFs have the ability to inhibit cancer cell apoptosis, increase the growth of cancer cells, and activate tumor angiogenesis." (PMID 28828003, 2017). "In particular, the tumor-suppressor caveolin-1, a fundamental member of caveolae, plays a key role in the control of the Ca2+-dependent apoptotic pathway and regulates fundamental mitochondrial functions during tumor growth." (PMID 28913175, 2017). "And in particular after radiation treatment the more radioresitant PC3(−)HS5(−)-derived tumors displayed an increased immunoreactivity to FAP and Tagln in the stromal compartment, which demonstrated a more reactive tumor stroma after radiation as well as a more prominent staining of epithelial Cav1." (PMID 28112237, 2017). "In addition, cav-1-/- mice crossed with tumor prone MMTV/PyMT mice were reported to have an accelerated appearance of dysplastic foci in mammary glands and were later shown to have an increased number of lung metastases." (PMID 28187162, 2017). "As a result, cav-1 expression could potentially be a useful tumor marker to aid clinicians in better diagnoses, more accurate prognoses, and may be a powerful tool in determining the best course of therapy for patients." (PMID 28187162, 2017). "The conflict roles of Cav-1 in tumor progression may be partly explained by the observation that Cav-1 has several peptide domains with opposing functions." (PMID 28546853, 2017). "Mechanistically, inhibition of VEGFR-2 and inhibition of eNOS-dependent vascular leakage may all be related to the tumor-suppressive function of Cav1." (PMID 29100301, 2017). "It has been hypothesized that Cav-1 may participate in focal adhesion turnover, with some studies suggesting that it may act either as a tumor suppressor, or as a tumor-promoting factor, depending on the cellular context." (PMID 29371975, 2017). "We also investigated the relationship of CAV-1 SNPs with clinical and histological features of BC, including tumor size, lymph node metastasis, and the statuses of estrogen receptor (ER), progestogen receptor (PR), human epidermal growth factor receptor 2 (Her-2), and Ki67." (PMID 29207674, 2017). "To mimic the human situation we performed co-implantations of Cav1-silenced PC3(−) tumor cells in combination with Cav1-silenced or Cav1-expressing HS5 fibroblasts by subcutaneous transplantations onto the hind limb of NMRI nude mice and irradiation treatment after manifestation of the tumor." (PMID 28112237, 2017). "CAV1 is a tumor suppresser, and inhibition of CAV1 promotes cell proliferation and invasion." (PMID 28490334, 2017). "While, in humans, a decrease in expression of Cav1 in tumour stroma is generally considered to be a marker of poor prognosis, increases in Cav1 in CAS have also been documented to be associated with higher tumour aggressiveness." (PMID 28531107, 2017). "CAV1 mRNA and protein levels were downregulated during cell transformation by oncogenes, such as Ha-Ras, v-Abl, Myc, and Neu, suggesting a negatively regulatory role of CAV1 in tumor development." (PMID 29097801, 2017). "Next we compared Cav-1 expression in normal and tumor tissues obtained from 100 cancer patients." (PMID 29141593, 2017). "However, reduced CAV1 protein levels were observed in most tumor cells compared with adjacent normal cells (49/50 cases) in our IHC analysis." (PMID 29097801, 2017).
tumor (continued). "Thus, cavtratin is considered a promising candidate for the inhibition of tumor progression, and Cav1 is considered a putative tumor-suppressor gene." (PMID 29100301, 2017). "Therefore we examined the impact of stromal Cav1 expression for tumor growth and sensitivity to ionizing radiation (IR)." (PMID 28112237, 2017). "In CAV1-knockout mouse models, tumor progression occurs and some different epithelial and stromal mechanisms seem to be involved in cyclin D1 up-regulation and increased RB phosphorylation in cancer cells and activation of the mTOR-S6 kinase pathway in myofibroblasts." (PMID 29099748, 2017). "We then aimed to test whether a more reactive fibroblastic tumor stroma with presumably reduced Cav1 expression accounts for the increased radiation resistance observed in PC3(−) xenograft tumors." (PMID 28112237, 2017). "Caveolin-1 and Cav-2 show opposite effects in distinct studies of tumor-induced angiogenesis." (PMID 29250058, 2017). "Several studies implicate that Cav-1 is involved in a tumor suppression in vitro and in vivo." (PMID 28828003, 2017). "The impact of Cav-1 on cancer progression, whether it is expressed in the tumor cells or stromal cells, seems to be complex and debatable." (PMID 28828003, 2017). "However, it remains unanswered how Cav-1 provokes opposite effects in different cancers or different phases of tumor progression." (PMID 29141593, 2017). "Caveolin-1 (CAV1) is an integral membrane protein that plays a dual role in tumor progression." (PMID 29340103, 2017). "Cav-1−/− mice showed reduced tumor growth and vessel density." (PMID 29250058, 2017). "As a consequence, our data suggest that the level of CAV1 expression in HCC patients may be an important determinant for defining the tumour cell response to TGF-β signalling." (PMID 29022911, 2017). "Notably, in a study of GC, Cav-1 mRNA expression was lower in cell lines derived from a primary tumor, but it increased in cell lines originating from distant metastases." (PMID 28828003, 2017). "Peculiar Src expression and kinase activity have been found in a number of different tumours, including GCs; these changes in expression could upregulate tyrosine phosphorylation of Cav-1 and inhibit the effects of the cell membrane on EGFR endocytosis." (PMID 27105508, 2016). "However, endogenous activation of Cav-1 (Cav-1 Y14D group) significantly enhanced tumor dissemination to the lungs, and more metastatic foci were observed." (PMID 26919102, 2016). "It should be clarified in which cellular context caveolin 1 functions as a tumor suppressor or an oncogene and whether altered intracellular cholesterol levels by caveolin 1 could suppress or promote cancer progression." (PMID 27973397, 2016). "Silencing of Cav-1 in prostate stroma cells induced a stroma phenotype effective in stimulating local androgen synthesis, angiogenesis, invasion and metastasis, suggesting that low Cav-1 expression in tumor stroma directly supports tumor growth." (PMID 27764093, 2016). "During the early stages of tumor progression, CAV1 negatively controls cell cycle progression and restrains cell proliferation, whereas accumulating evidence suggests that CAV1 has an opposite role in advanced stages of cancer, promoting cell growth and metastasis." (PMID 26672765, 2016). "In addition, low tumor Cav-1 in patients with GS 6 + 7 (10-year P-EFS 45 ± 17%) had significantly shorter cancer specific survival than those with high tumor Cav-1 in this subgroup (10-year P-EFS 79 ± 5%)." (PMID 27764093, 2016). "Glutaminolysis – CAV1 in the alternative tumour energy pathway?" (PMID 27852311, 2016). "Here, the authors show that caveolin-1 can down-regulate global membrane protein endocytosis in hypoxic cells with potential implications for targeting the hypoxic 3microenvironment of aggressive tumours." (PMID 27094744, 2016). "Cox regression for tumor stroma Cav-1 of patients followed by watchful waiting." (PMID 27764093, 2016).
tumor (continued). "Consequently, research findings suggest that CAV1, which is altered in several cancer types, influences tumour development or progression by controlling metabolism." (PMID 27852311, 2016). "Consequently, CAV1 was found to be overexpressed in cancers of liver, colon, breast, kidney, lung, among others, and acts as a tumour promoter or suppressor depending on tumour type and stage." (PMID 27852311, 2016). "However, the specific roles of Cav-1 in migration of circulating tumor cells during hematogenous metastasis requires further investigation." (PMID 26919102, 2016). "More studies are required to elucidate the influence of CAV1 on glucose utilisation and glycolytic enzymes, especially in CAV1 overexpressing tumours, and to determine whether glycolysis modulates the expression and function of CAV1 in normal and cancer cells." (PMID 27852311, 2016). "In particular, loss of Cav-1 could be a marker of glycolysis in CAFs that increase in cancer cells OXPHOS rate, ATP production, and proliferation, by supplying tumor cells with lactate in a paracrine manner." (PMID 27595103, 2016). "This can probably not be the only explanation as some SMA positive cells in the tumor stroma, presumably cancer associated fibroblasts (CAFs), were Cav-1 positive whereas others were negative." (PMID 27764093, 2016). "Mechanistically, this pathway involved increased phosphorylation of key cell motility kinases Akt and Src, and reconstitution experiments in ClpP-silenced cells identified the membrane microdomain adapter caveolin-1 as a novel, oxidative, stress-regulated mediator of tumor cell motility." (PMID 27389535, 2016). "Cav-1 in tumor stroma also gave prognostic information for patients with GS 6–7 graded tumors." (PMID 27764093, 2016). "Interestingly, rBmαTX14 induced the expression of cav-1 and nnt-1, which play various roles in tumor progression." (PMID 27611314, 2016). "Because Y14F mutation diminishes metastasis without inhibiting the tumor suppressor function of CAV1, Y14 phosphorylation emerges as an attractive therapeutic target to prevent metastasis without altering beneficial traits of CAV1." (PMID 27259249, 2016). "ERK1/2 activity is regulated by CAV1 in different tumor types." (PMID 27487136, 2016). "Finally, Cav-1 knockdown significantly suppressed tumor colonization in the lungs and distant metastases in animal models." (PMID 26919102, 2016). "Further, immunostaining of primary tumors was utilized to analyze the fiber alignment and organization of the tumor stroma in the presence of WT or Cav1 KO pMEFs, as alignment of collagen fibers in the tumor microenvironment has been shown to enhance tumor cell migration and invasion." (PMID 26179155, 2015). "Intriguingly, opposing evidence supports a role for Cav-1 as a tumor-promoting protein." (PMID 26431273, 2015). "In vivo, Cav-1 depletion significantly attenuates tumor initiation and growth." (PMID 26065715, 2015). "Anti-α5β1 integrins therapy might therefore be a new therapeutic option for the “R1” subgroup of patient exerting low levels of Cav1 expression in order to prevent the development of metastasis but also the development of primary “R1” tumours." (PMID 26474461, 2015). "Recently, evidence suggests a function for Cav-1 in tumor stroma." (PMID 26431273, 2015). "Taken together, these data suggest that T-cell malignancies with higher CAV1 expression correlate with a GEP of possessing a more inflammatory tumor microenvironment and may hold more metastatic potential." (PMID 26566034, 2015). "A possible explanation for the conditional role of CAV1 as both tumor promoter and suppressor is the interaction of CAV1 with other effector molecules that may directly or indirectly interact with or affect CAV1’s function." (PMID 26112043, 2015).
tumor (continued). "Further work is required to elucidate whether Cav1-dependent resistance-promoting signals from ECs can be separated from Cav1-dependent stromal signals that restrict tumor growth and may thus allow a safer targeting of Cav1 mediated radiation resistance." (PMID 25985209, 2015). "Elucidation of Cav-1 in cancer development and progression may be significant for improving patient prognosis and preventing tumor onset." (PMID 26431273, 2015). "However, we show here for the first time that Cav1 levels in the tumor microvasculature are important to the outcome of radiotherapy." (PMID 25985209, 2015). "PANTHER enrichment analysis of genes upregulated in the CAV1-High tumor microenvironment." (PMID 26566034, 2015). "In addition to direct silencing of Cav-1 to target cancer cells, it is necessary to protect Cav-1 from downregulation in tumor stroma." (PMID 26431273, 2015). "Thus, CAV1 would serve as a promoter of tumour initiation and progression by enhancing β-catenin-related transcription." (PMID 26307673, 2015). "Cav-1 expression was assessed in cell lines, mouse models, and patient samples, and knocked down in order to compare changes in proliferation, invasion, migration, response to chemotherapy and radiation, and tumor growth." (PMID 26065715, 2015). "Whether the downregulation of Cav1 in tumor cells is correlated with changes in the mechanical phenotypes will need to be confirmed in the future." (PMID 26189182, 2015). "Monitoring the expression of Cav1 might be a useful tool for a more reliable evaluation of tumour propensity for metastasis, and to identify patients who could benefit from a new and more personalized medicine." (PMID 26474461, 2015). "Next, we correlated Cav-1 expression (dichotomized by low versus high scores) in the tissue microarray with clinical characteristics such as tumor histopathologic grade, serum CA19-9, and clinical outcomes including relapse-free survival (RFS), disease-free survival (DFS), and overall survival (OS)." (PMID 26065715, 2015). "Caveolin-1 (Cav-1) is both a tumor suppressor and an oncoprotein." (PMID 26431273, 2015). "Cav1 staining was found to be largely weaker in “R1” tumour specimen." (PMID 26474461, 2015). "Together, these results suggest Cav-1 is important in promoting tumor resistance to chemotherapeutics in PC cells and that targeted Cav-1 knockdown sensitizes PC cells to genotoxic agents such as gemcitabine and 5-fluorouracil through activation of apoptosis and inactivation of pro-survival signals." (PMID 26065715, 2015). "Cav-1 can act as both a tumor suppressor and as a tumor promoter." (PMID 25756273, 2015). "If α5β1 integrins did not drive EMT, they seemed to play a crucial role in the motile and invasive phenotype acquired by cells expressing low level of Cav1 as their ligand FN clearly boosted the evasion of shRNAcav-1-cells out of the tumor spheres in contrast to control cells." (PMID 26474461, 2015). "CAV1 is thought to function as a tumor suppressor in a variety of cellular backgrounds." (PMID 26054531, 2015). "Mechanically, we find that cav-1/AKT/mTOR pathways account for the anti-tumor effects of baicalein." (PMID 25957503, 2015). "Furthermore, we confirmed that PTEN expression decreases CAV1/BCAT immuno-complex in murine tumour samples and affects the transcription of known β-catenin targets, MYC and CCDN1." (PMID 26307673, 2015). "However, tumor growth delay of MPR31-4 tumors grown on Cav1 knockout mice to a single high-dose irradiation with 20 Gray was more pronounced compared with tumors grown on wild-type mice." (PMID 25985209, 2015). "However, the precise role of Cav1 in tumor progression appears to be unclear, with studies showing both increased and decreased expression in various types of cancer." (PMID 26179155, 2015). "Cav-1 may be a duplex signal during cancer progression, and its expression status might be closely correlated to tumor stage." (PMID 26431273, 2015).
tumor (continued). "The downregulation of Cav-1 and Acsvl3 suggested a reduction of tumor growth." (PMID 25015569, 2014). "Analysis of DNA methylation in the CAV1 gene promoter of RMS cell lines and tumor samples showed hypermethylation in the promoter-associated CpG island in 5 out of 6 ARMS cell lines but in any of the other cell lines used in the experiment nor in the two ARMS tumor samples." (PMID 25313138, 2014). "According to this study, CAV1 may be transferred from tumour cells to stromal cells (through exosomes or direct cell–cell transfer of membranes)." (PMID 24500501, 2014). "Despite a growing body of evidence on Cav-1 implication in tumorigenesis, whether Cav-1 serves as a tumor suppressor or as an oncogene remains unclear." (PMID 24949874, 2014). "However, the oncogenic and tumor suppressor function of caveolin-1 have been reported to occur within a tumor type." (PMID 25397596, 2014). "It was shown that CAV1 expression difference is tumor cells type-dependent." (PMID 25180681, 2014). "Several studies have recently assessed the potential function of Cav-1 in tumor progression." (PMID 24949874, 2014). "We have checked the effects of CAV1 knockdown in MHCCLM3 on long-distance tumor metastasis in vivo." (PMID 25180681, 2014). "Interestingly, Cav-1 expression was strong and confined mainly to the stroma in paraneoplastic and normal tissues but was only detected occasionally in tumor stroma." (PMID 24949874, 2014). "However, bare- or tiny-visible locoregional metastasis or metastatic tumors were found in mice lungs that were orthotopically implanted with the MHCCLM3 cells of CAV1 knockdown tumor." (PMID 25180681, 2014). "It was shown that, depending on the histogenesis of the tumor, caveolin-1 may function as a tumor suppressor gene as well as an oncogene." (PMID 24533441, 2014). "We then evaluated the effects of Cav-1 overexpression on tumor growth in vivo." (PMID 24427291, 2014). "Hence, caveolin-1 is thought of as a putative tumor suppressor of which its decreased expression allows for cancer progression." (PMID 25594072, 2014). "To examine whether the level of Cav-1 in tumor tissues helps to predict survival of HCCs after liver resection, we followed up the HCC patients recruited in this study." (PMID 24454730, 2014). "In addition it was reported that caveolin-1 expression in tumor cells affects the clinical outcome and prognosis of patients with squamous cell carcinoma of the lung." (PMID 25015569, 2014). "Additionally, Src kinase-dependent caveolin-1 (Cav1) phosphorylation increases focal adhesion turnover, RhoA activation, and tumor cell migration in a galectin-3-dependent manner." (PMID 24982845, 2014). "Cav-1 may have an oncogenic or tumor suppressor role depending on the cell type; however, further investigation of Cav-1 expression and the possible underlying mechanisms are required." (PMID 25202343, 2014). "However, analysis of tumour metastasis to the lung in the same mice showed an increase for CAV1-expressing cells in comparison with mock cells (Fig. 4g1 and g2, respectively)." (PMID 24500501, 2014). "CAV1 has been characterized to possess a dual-function in cancer progression as a tumor suppressor and oncogene, and its reexpression has been implied to be necessary for metastasis in certain types of cancer to promote cell migration and invasion, for example, breast, lung, and prostate." (PMID 25104873, 2014). "Treated tumor shows a low signal of caveolin-1 protein due to 4HPR-HSA." (PMID 25015569, 2014). "CAV1 has been thoroughly characterized in many cancers due to its ability to regulate cell cycle progression and intracellular signal transduction, and it has been shown to act both as a tumor suppressor or tumor promoter depending on the cellular background." (PMID 25313138, 2014). "However, studies have found that NOS productions are transcriptionally overexpressed in human tumor and Cav-1(−/−) stromal cells." (PMID 25202343, 2014).